NT5C3B (5'-nucleotidase, cytosolic IIIB)
Description:
Specifically hydrolyzes 7-methylguanosine monophosphate (m(7)GMP) to 7-methylguanosine and inorganic phosphate. The specific activity for m(7)GMP may protect cells against undesired salvage of m(7)GMP and its incorporation into nucleic acids. Also has weak activity for CMP. UMP and purine nucleotides are poor substrates.
Synonyms: NT5C3L; MGC20781; cN-IIIB; CNIIIL
Tractability: Small molecule: a structure with a bound ligand is known; a high-quality ligand is known. PROTAC: ubiquitination databases record sites on it; its protein half-life has been measured.
Target class: Enzyme; Hydrolase
Gene: Protein-coding gene on chromosome 17 (41,825,057 to 41,836,260, reverse strand). Ensembl gene ENSG00000141698.
Subcellular location: Cytoplasm
Pathways (Reactome):
Metabolism of RNA: mRNA decay by 3' to 5' exoribonuclease
Gene Ontology:
Molecular function: 5'-nucleotidase activity; magnesium ion binding
Biological process: nuclear-transcribed mRNA catabolic process, deadenylation-dependent decay
Cellular component: cytoplasm; cytosol
Genetic constraint (gnomAD): Loss-of-function variants: 22 observed, 22.66 expected, observed/expected ratio (o/e) 0.97, 90% interval 0.69 to 1.39. The upper end of that interval is the gene's LOEUF score, 1.39, which puts it in group 5 of 6, group 1 being the genes least tolerant of losing a copy. Missense variants: 195 observed, 209.75 expected, observed/expected ratio (o/e) 0.93, 90% interval 0.83 to 1.05. Synonymous variants: 82 observed, 74.24 expected, observed/expected ratio (o/e) 1.1, 90% interval 0.92 to 1.33.
Homologues: Orthologues: chimpanzee NT5C3B (100% identical), dog NT5C3B (93% identical), rat Nt5c3b (90% identical), mouse Nt5c3b (90% identical), pig NT5C3B (88% identical), macaque NT5C3B (83% identical), guinea pig NT5C3B (61% identical), tropical clawed frog nt5c3b (61% identical), Drosophila melanogaster cN-IIIB (37% identical), Caenorhabditis elegans F25B5.3 (36% identical), Caenorhabditis elegans Y10G11A.1 (36% identical). Paralogues in human: NT5C3A (55% identical).
Diseases named in the same sentence as NT5C3B in open-access papers:
NT5C3B is named in the same sentence as 4 diseases in open-access papers, as found by Europe PMC text mining. Sharing a sentence is not in itself a finding about the gene and the disease. The quoted sentences say what the papers report.
breast carcinoma (1 paper, 2025). "Cathepsin E can mediate the effects of APBB1IP, NT5C3B, and ZNF66 on HER2-negative breast cancer, as well as the effects of DHRS9, CDK12, and CD247 on HER2-positive breast cancer." (PMID 39944834, 2025).
leukemia (1 paper, 2026). A malignant (clonal) hematologic disorder, involving hematopoietic stem cells and characterized by the presence of primitive or atypical myeloid or lymphoid cells in the bone marrow and the blood. "High expression of JUP, NT5C3B, MYC, GATA3, PTK7, CNP, and ICOSLG clearly differentiated the leukemia from the non-leukemia group." (PMID 41596324, 2026). "High expressions of NT5C3B, MYC, and CNP were also able to differentiate between the non-leukemia and MRD-positive groups, while only MYC could distinguish between MRD-negative and MRD-positive groups." (PMID 41596324, 2026).
cancer (2 papers, 2021 to 2026). A tumor composed of atypical neoplastic, often pleomorphic cells that invade other tissues. "In addition, its established biochemical function in nucleotide metabolism makes a compelling case for prioritizing NT5C3B in functional validation studies related to cancer and cell survival." (PMID 41596324, 2026).
NT5C3B also shares sentences with these, for which no sentence is quoted: atherosclerosis (1 paper).